TCF4 (transcription factor 4)
Diseases named in the same sentence as TCF4 in open-access papers (continued):
Sharing a sentence is not in itself a finding about the gene and the disease.
Intellectual disability (continued). "We here investigated whether TCF4 haploinsufficiency, which in humans causes non-syndromic forms of intellectual disability and PTHS, affects adult hippocampal neurogenesis, a process that is essential for hippocampal plasticity in rodents and potentially in humans." (PMID 33228529, 2020). "A cohort of 67 individuals with genetically confirmed PTHS and three individuals with intellectual disability and a variant of uncertain significance (VUS) in TCF4 were studied." (PMID 38571311, 2024). "Deletions in the 5′ coding region of the TCF4 gene have been described in patients with mild nonsyndromic intellectual disability." (PMID 34748727, 2021). "TCF4 is a basic helix–loop–helix transcription factor previously associated with SCZ, ASD, and intellectual disability and has been shown to regulate spine densities in the cortex and the hippocampus." (PMID 31142819, 2021). "Mutations in TCF4, MEF2C, UBE3A, ZEB2 or ATRX cause phenotypically overlapping, syndromic forms of NDDs with severe intellectual disability, epilepsy and microcephaly." (PMID 31988313, 2020). "More 5′ located deletions in TCF4 have been identified in individuals with intellectual disability who lack other features of PTHS2,10." (PMID 33037178, 2020). "The present findings indicate that haploinsufficiency for the intellectual disability- and PTHS-linked transcription factor TCF4 not only affects embryonic neurodevelopment but impedes neurogenesis in the hippocampus of adult mice." (PMID 33228529, 2020). "Heterozygous mutations in TCF4, the orthologue of da, lead to PTHS syndrome, which is characterized by intellectual disability." (PMID 32641419, 2020). "To address the relationship between mutation of these transcripts and phenotype, we report a three-generation family segregating mild intellectual disability with a chromosomal translocation disrupting TCF4." (PMID 27179618, 2016). "Interestingly, we also observed that 28 genes actively expressed at this stage, including genes such as NFIA, CDH13, TCF4, and DLG2, were associated with intellectual disabilities, autism spectrum disorders, irritability, and depression." (PMID 39452151, 2024). "This may mimic the changes in human TCF4 expression levels linked to risk variants in intronic TCF4 regions associated with SZ, MDD, and intellectual disability." (PMID 33037178, 2020). "On the other hand, loss of function TCF4 mutations have been found in patients with Rett syndrome-like phenotypes, ASD and Pitt–Hopkins syndrome, which is characterized by ASD, intellectual disabilities, and microcephaly." (PMID 28321286, 2017). "Since IGF2 has a role in learning and memory and PTHS patients have profound intellectual disability, TCF4 regulation of IGF2 expression may be a determinant of cognitive dysfunction." (PMID 24058414, 2013). "Mutations in TCF4 cause a devastating autism spectrum disorder known as Pitt–Hopkins syndrome, characterized by a range of aberrant phenotypes including severe intellectual disability, absence of speech, delayed cognitive and motor development, and dysmorphic features." (PMID 33414364, 2021). "Notably, TCF4 target genes were significantly enriched for risk genes of neurodevelopmental disorders, including SCZ, autism and intellectual disability, suggesting TCF4 perturbation could be a major contributor to PSD by regulating many other risk genes at the early stage of neurodevelopment." (PMID 35965434, 2022). "In addition to ASCL1 and NEUROG2, other neurodevelopmental transcriptional regulators such as, MEF2C (syndromic mental retardation) and ZEB2 (MWS) were also differentially expressed in TCF4-depleted cells." (PMID 24058414, 2013).
melanoma (42 papers, 2009 to 2025). A malignant, usually aggressive tumor composed of atypical, neoplastic melanocytes. "In fact, β-catenin/TCF-4 associates with nuclear VE-cadherin, enhancing the ability of melanoma cells to undergo VM." (PMID 40000790, 2025). "The same study showed that loss of LEF1 and gain of TCF4 expression was associated with melanoma progression, involving changing from a proliferative to an invasive phenotype." (PMID 36675114, 2023). "MITF levels are inversely correlated with transcription factor 4 (TCF4) and EZH2, which promote the mesenchymal-like state of melanoma associated with the suppression of antigen presentation." (PMID 40108693, 2025). "VE-cadherin’s abnormal expression and phosphorylation by FAK in metastatic melanoma cells promote the aggressive VM phenotype through β-catenin cooperation and enhanced TCF-4-dependent transcription." (PMID 40000790, 2025). "In melanoma, transcription factor 4 (TCF4) binds to GLUT3 and enhances its expression, leading to resistance against vemurafenib." (PMID 40264038, 2025). "By altering the tumor’s phenotype, TCF4 enables melanoma cells to survive and proliferate in an immune-suppressive environment, making them more resistant to immune checkpoint blockade." (PMID 40872475, 2025). "Accordingly, a Tcf4 knockdown in melanomas improved the therapeutic effect of anti-PD1 antibodies in vivo." (PMID 38561348, 2024). "In vemurafenib resistant cell lines, TCF4 knockdown sensitized melanoma cells to vemurafenib in a Glucose transporter 3 (GLUT3)-dependent manner, thereby decreasing lactate production." (PMID 38426087, 2024). "Targeting TCF4 in “mesenchymal-like” melanoma increased immunogenicity and yielded a targeted therapy benefit." (PMID 38426087, 2024). "The IL‐10 promoter contained TCF binding motifs for regulation by the β‐catenin/TCF‐4 complex in human melanoma." (PMID 35864742, 2023). "In a recent study, a regulatory network dependent on TCF4/BRD4 was linked to the development of resistance to both targeted and immune checkpoint therapies in melanoma." (PMID 38139110, 2023). "TCF4 exerts oncogenic effects by promoting the proliferation, invasion, and chemoresistance of melanoma, lung, colorectal, and breast cancers." (PMID 35406121, 2022). "A previous report has shown that TCF4, an E-box binding transcription factor (E-protein), closely participates in the wide spread of melanoma in response to PGC1α suppression." (PMID 33917757, 2021). "Consistent with previous studies, we found that activated Wnt/β-catenin signaling, which involves LEF1, TCF4, and β-catenin is highly increased in melanoma." (PMID 32933177, 2020). "Abnormally increased levels of nuclear LEF1, TCF4, and β-catenin, which are essential transcriptional components of Wnt/β-catenin signaling, were observed in A375, A2058, and G361 melanoma cells." (PMID 32933177, 2020). "The interaction between beta-catenin, lymphoid enhancer-binding factor 1 (LEF1), and transcription factor 4 (TCF4) was studied in order to see its effects on melanoma." (PMID 31934531, 2019). "It was observed that the increase in TCF4 and decrease in LEF1 was associated with an invasive transformation of melanoma, in contrast with epithelial tumors where the upregulation of beta-catenin interaction factor LEF1 was seen to promote EMT." (PMID 31934531, 2019). "Ectopic expression of miR-25 in melanoma cells induced β-catenin accumulation in nuclear and inhibited TCF4 (T cell factor 4) activity, as well as the expression of c-Myc and Cyclin D1." (PMID 27801786, 2016). "miR-25 activated the WNT pathway by targeting DKK3, thus not only enhancing the ability of melanoma to infiltrate into tumor tissue but also facilitating tumor invasion and metastasis by upregulating TCF4, c-Myc, and Cyclin D1 in vitro and in vivo." (PMID 27801786, 2016).
melanoma (continued). "Then, nuclear localization of β-catenin was decreased in response to pCDNA-DKK3 transfection, suggesting that miR-25 upregulation is sufficient to induce cell proliferation and β-catenin/TCF4 pathway, at least in some melanoma cells." (PMID 27801786, 2016). "VCAN expression is elevated in our invasive Motif 1 NZM cells, which is in agreement with a recent report that VCAN is up-regulated in invasive human melanoma cells via a TCF4/AP1-mediated mechanism." (PMID 20041153, 2009). "However, a recent report outlined how a TCF4-dependent gene regulatory network conferred immunotherapy resistance in melanoma, consistent with previous reports of enhanced Wnt signaling in immunotherapy resistance." (PMID 40361430, 2025). "Another key transcription factor, transcription factor 4 (TCF4), promotes a mesenchymal-like state in melanoma cells that reduces susceptibility to T cell infiltration, downregulates antigen presentation, and impairs interferon signaling, all of which are critical for ICI resistance." (PMID 40872475, 2025). "Targeting TCF4 can enhance the sensitivity of melanoma to ICI and targeted therapy." (PMID 39334490, 2024). "recently reported the role of TCF4-driven mesenchymal melanoma cells in immunotherapy resistance." (PMID 39697983, 2024). "In addition, both BET degrader as well as TCF4 knockdown sensitized melanoma cells to BRAF and MEK inhibitors in vitro." (PMID 38561348, 2024). "The data demonstrated that melanoma TCF4 impinged on T-cell killing activity in vitro." (PMID 38561348, 2024). "In the melanoma population, TCF4 is specifically expressed in MES cells." (PMID 38561348, 2024). "It has been reported that PGC1α suppresses distant metastasis by mediating a transcriptional circuit comprising the inhibitor of DNA binding 2 (ID2) and transcription factor 4 (TCF4, also called ITF-2 or E2-2), independently of metabolic reprogramming in melanoma." (PMID 33917757, 2021). "Indeed, aberrant Wnt/β-catenin signaling pathway expression, which increases nuclear β-catenin, LEF1, and TCF4 levels, has been observed in various cancers, including melanoma." (PMID 32933177, 2020). "Additionally, it has been reported that the differential expression of LEF1 and TCF4 determines the proliferative and invasive potentials of melanoma subtypes." (PMID 32933177, 2020). "Moreover, ectopic expression of miR-25 in melanoma cells inhibits the activity of TCF4, cyclin D1, and c-Myc." (PMID 30866509, 2019). "Moreover, investigations into intrinsic resistance mechanisms at immune checkpoint blockade (ICB) sites through comprehensive single-cell profiling of melanoma have shown that targeting transcription factor 4 (TCF4) expression increases sensitivity to ICBs and targeted therapies." (PMID 39935429, 2025). "Similarly, Pozniak and colleagues showed that overexpression of TCF4 leads to decreases in TNF-α and T cell activation and suppression of TCF4 elicits inflammation, including increases in IFNs, thereby increasing the sensitivity of immune checkpoint inhibitors used to treat melanoma." (PMID 38470486, 2024). "Although previous studies indicate that Wnt/β-catenin signaling with LEF1, TCF4, and β-catenin expression is closely associated with melanoma growth and progression, it is still unclear whether LEF1 acts as a proliferative factor in melanoma." (PMID 32933177, 2020). "Genetic targeting of TCF4 or using bromodomain and extra-terminal motif (BET) inhibitors has been shown to enhance melanoma cell recognition by T cells in co-culture experiments, increasing the sensitivity of melanoma lesions to ICB in mouse models." (PMID 40861441, 2025). "Transcription Factor 4 (TCF4) plays a role in Wnt/β-catenin signaling and is upregulated in BRAF-inhibitor resistant melanoma cells." (PMID 38426087, 2024).
melanoma (continued). "Remarkably, the authors found that the basic helix-loop-helix transcription factor TCF4, a driver gene of the MES-related epithelial/mesenchymal transition (EMT) signature, was specifically expressed in the subtype of MES melanoma cells." (PMID 38561348, 2024). "Differentiated/proliferative phenotype melanoma cells preferentially express LEF1 and dedifferentiated/invasive phenotype cells usually express TCF4." (PMID 36675114, 2023). "PGC1α enhances the transcription of inhibitor of DNA binding 2 (ID2), which in turn binds to and inactivates the transcription factor 4 (TCF4), leading to the downregulated expression of metastasis-related genes and thus impeding melanoma metastasis." (PMID 36003368, 2022). "Using WGCNA combined with supervised machine learning algorithms, we identified a novel CAFs-related panel, including six genes (CDK14, SYNPO2, TCF4, GJA1, CPXM1, TFPI), which can distinguish the response of melanoma patients under anti-PD-1 immunotherapy." (PMID 35479936, 2022). "In melanomas, genes coordinately expressed with GPC6 were largely those involved in cell adhesion and migration including INHBA, PDGFC, PDGFRA, PPAP2B, SPRX2, TCF4, and TNFAIP6 and ZEB1." (PMID 31199813, 2019). "PGC-1α overexpression in melanoma cells by adenovirus infection suppressed metastasis via the direct regulation of inhibitor of DNA binding protein 2 (ID2) and the inhibition of transcription factor 4 (TCF4)-mediated gene transcription." (PMID 30400212, 2018). "It has already been shown that the expression of TCF4 and LEF1 is inversely correlated in melanoma, and LEF1 suppresses TCF4 expression in a β-catenin-independent manner." (PMID 27351373, 2016). "Finally, to further assess the functional contribution of Wnt/β-catenin transcriptional output to melanoma cell phenotype switching we ablated the expression of TCF4 and LEF1, the TCF family members predominantly expressed in melanoma cells." (PMID 34819356, 2022). "Additionally, TCF4 is reported to regulate the transcription of pro-metastatic and EMT-related genes in malignant melanoma and lung cancer." (PMID 35406121, 2022). "The same was observed in melanoma: PGC-1α blocks the invasive capacity of cancer cells, and by knocking down PGC-1α; invasiveness is rescued through the transcription factor 4 (TCF4)–focal adhesion kinase (FAK) signaling axis, that modulates cell–cell and cell–matrix interactions." (PMID 34150624, 2021). "Predominant expression levels of LEF1 and β-catenin, but not TCF4, have been observed in highly metastatic melanoma cells such as MM-AN, MM-BP, RPM-EP, and MM-RU cells." (PMID 32933177, 2020). "Both TCF4 and LEF1 are Wnt target genes but differential expression changes have been demonstrated in other models: as an example, in melanoma studies, LEF1 is prominent in differentiated/proliferative cells whilst dedifferentiated/invasive cells express TCF446." (PMID 29531810, 2018). "By co-immunoprecipitation we detected TCF4 and Snail binding to full length CtBP1 (in the CtBP1-expressing melanoma cell clones), but none with CtBP1splice." (PMID 19216735, 2009). "In addition, decreased β-catenin but not TCF4 levels were observed in LEF1 knocked-down melanoma cells." (PMID 32933177, 2020). "The transcription of miR-125b is induced by TCF4 (transcription factor 4), and one of the direct targets of miR-125b is a transcript of NEDD9 (neural precursor cell expressed developmentally down-regulated protein 9), which is involved in the mesenchymal movement of melanoma cells." (PMID 30866509, 2019).
hepatocellular carcinoma (40 papers, 2013 to 2025). A malignant tumor that arises from hepatocytes. "However, such deficiency of Nrf1 led to downregulation of TCF4 (as a critical transcription partner of the β-catenin coactivator) in human Nrf1-silenced hepatoma xenografts and metastatic tumor tissues." (PMID 32273945, 2020). "Furthermore, the regulation of miR-181a/b expression has been associated with TCF4 expression in hepatocellular carcinoma." (PMID 25910082, 2015). "Reference 1 Gao J, Dai C, Yu X, Yin X-B, Zhou F. Circ-TCF4.85 silencing inhibits cancer progression through microRNA-486-5p-targeted inhibition of ABCF2 in hepatocellular carcinoma." (PMID 37231579, 2023). "Transcriptome analysis of human hepatocellular carcinoma cells (HepG2) under leucine deprivation revealed that hsa-miR-663a and hsa-miR-1469 were altered in a transcription factor 4-dependent manner." (PMID 35990342, 2022). "Previous studies revealed that TCF4 promotes hepatocellular carcinoma progression through various molecules and signalling." (PMID 33951279, 2021). "In colorectal and hepatocellular carcinoma, HIF1α was found to compete with TCF-4 for direct binding to β-catenin enhancing transcriptional HIF1α activity." (PMID 29422917, 2017). "For instance, over expression of miR 122 downregulates hepatocellular carcinoma by controlling the expression of Wnt 1, β-catenin and TCF-4, which is ranked 1st in our experiment." (PMID 28122525, 2017). "How platelet-tumor cell binding enhances TCF4 expression in hepatoma cells needs further investigation." (PMID 27542264, 2016). "Fifth, microarrays showed that a total of 214 genes were markedly changed in the tumor tissues after anti-platelet intervention, and we confirmed repression of TCF4 promoted hepatoma cell differentiation." (PMID 27542264, 2016). "We demonstrated that TCF4 was a pivotal differentiation regulator in hepatoma cells, and TCF4 repression promoted HepG-2 cell differentiation and inhibited tumor formation." (PMID 27542264, 2016). "Although previous studies showed that TCF4 promotes hepatocellular carcinoma through the Wnt pathway, the role of TCF4 in liver regeneration remains unknown." (PMID 33951279, 2021). "Moreover, real-time PCR analysis revealed that β-catenin and TCF-4 increased mRNA levels of ABCD2 in both a hepatocellular carcinoma cell line and primary fibroblasts from an X-ALD patient." (PMID 23437103, 2013). "For example, FAT10 upregulated HOXB9 in hepatocellular carcinoma (HCC), through the β-catenin/TCF4 signaling pathway and facilitates HCC invasion in vitro." (PMID 36674743, 2023). "Interestingly, in the context of Wnt/β-catenin signaling-dependent liver tumorigenesis, it was suggested that TCF4 might act in concert with the FOXA factors to regulate hepatocellular carcinoma-specific Wnt target gene expression." (PMID 35140289, 2022). "For example, SOX10 facilitates the formation of a stable SOX10/T-cell factor (TCF)-4/β-catenin complex, subsequently contributing to tumorigenesis in hepatocellular carcinoma (HCC)." (PMID 25427424, 2014). "This aligns with a previous report of lower LEF-1 (and TCF4) levels (protein and mRNA) upon MSI2 depletion in SMMC-7721 hepatocellular carcinoma cells." (PMID 40301545, 2025). "In hepatocellular carcinomas, NOS2 is a Wnt β-catenin/Tcf-4 target gene that promotes tumorigenesis." (PMID 37346068, 2023). "UBD/FAT10, which we found to be hypomethylated in high BMI BE patients, is of interest as this gene has been shown to be overexpressed in hepatocellular carcinoma (HCC) and is thought to modulate the β-catenin/TCF4 pathway and drive HCC invasion and metastasis." (PMID 27795744, 2016). "In a hepatoma cell line, HINT1 inhibits activity of Wnt/ß-catenin signaling and gene transcription via TCF4." (PMID 24386364, 2013).
hepatocellular carcinoma (continued). "For example, transcription factor 4 (TCF4) binds to the AJUBA SEs and promoter to promote epithelial-mesenchymal transition (EMT) and metastasis in hepatocellular carcinoma (HCC), while MYCN invades and binds to enhancers to amplify tumor-specific transcriptional outputs in neuroblastoma." (PMID 41462308, 2025). "Furthermore, in hepatocellular carcinoma (HCC), Let-7 has been found to target transcription factor 4 (TCF-4), a key member of the WNT pathway." (PMID 38836981, 2024). "The transcription factor 4 (TCF4) and neuronal differentiation 1 (NeuroD1) can directly stimulate GPX4 transcription, thus inducing ferroptosis resistance in gastric cancer and hepatocellular carcinoma, respectively." (PMID 39624080, 2024). "In hepatocellular carcinoma, AJUBA is activated by TCF4 and participated in EMT." (PMID 35898403, 2022). "Because TCF4 (TCF7L2) is one of the major Wnt/β-catenin signaling-associated transcription factors and binds to Irs1 promotor in the rat hepatoma cell line H4IIE16, 21, the effect of dominant-negative TCF4 cDNA (DN-TCF4) on the regulation of Irs1 in primary hepatocytes was examined." (PMID 28710407, 2017).